CXCR4 (C-X-C motif chemokine receptor 4)
Diseases named in the same sentence as CXCR4 in open-access papers (continued):
Sharing a sentence is not in itself a finding about the gene and the disease.
tumor (continued). "This is consistent with observations in mouse models ofbreast cancer in which interventions affecting CXCR4 reduced both growth of theprimary tumor and metastasis." (PMID 18779872, 2008). "In the tumor in which CXCR4 immunodetection are unreactive, staining for CXCR4 occurred in inflammatory cells." (PMID 18826577, 2008). "We next examined the correlation between CD133 and CXCR4 expression as it was recently demonstrated that CD133+ CXCR4+ cells are involved in tumour metastasis." (PMID 18349830, 2008). "In the CRC tissues, CXCR4 immunoreactivity was found not only in cancer cells but also in lymphocytes in the tumour stroma." (PMID 18443596, 2008). "A furtheropportunity is offered by promoting strategies that downregulateCXCR4 pathways: CXCR4 expression in the tumor microenvironment ismodulated by factors such as hypoxia, nucleosides, andeicosanoids." (PMID 18779872, 2008). "In tumours, the MØs can promote tumour cell angiogenesis, invasion and survival by up-regulating genes such as GLUT-1, VEGF, CXCR4 and MIF and high levels of these tumour-associated macrophages (TAMs) can predict poor patient survival." (PMID 18507854, 2008). "In the normal colorectal epithelium adjacent to the tumour, weak immunoreactivity for CXCR4 was generally detected in the cytoplasm and plasma membrane of non-neoplastic epithelial cells." (PMID 18443596, 2008). "Here, we focussed on the immunostaining pattern for CXCR4 in cancer cells at the invasive fronts of tumours." (PMID 18443596, 2008). "In the case of tumor cells, this upregulation of CXCR4 by VEGFcan happen through an autocrine mechanism." (PMID 18779872, 2008). "A specific subpopulation of CD133+ CXCR4+ CSCs was recently identified as being responsible for tumour metastasis." (PMID 18349830, 2008). "CXCR4 has been shown experimentally to be crucial for cancer cell adhesion and/or migration, suggesting the involvement of CXCR4 in tumour invasion and metastasis." (PMID 18443596, 2008). "CXCR4 overexpression in NB cells increased in vitro cell growth under serum deprived conditions and in vivo tumour growth." (PMID 17925864, 2007). "We have shown that interfering with the CXCR4/CXCL12 axis using TN14003 in vitro will effectively inhibit tumor cell migration." (PMID 18001467, 2007). "In previous reports dealing with CXCR4 expression in neoplastic diseases nuclear, cytoplasmic, and membrane staining was found by means of immunohistochemistry." (PMID 17245339, 2007). "In 53.8% of malignant tumours, cytoplasmatic CXCR4 expression was medium or high (2/3) and 21.8% showed CXCR4 staining of the nucleus." (PMID 17245339, 2007). "Six out of 8 animals (75%) in the NB8-E6 group, and 7/8 mice (88%) in the group engrafted with NB8-CXCR4-C3 developed a tumour, thus showing a similar tumour take in mice engrafted with CXCR4-negative or CXCR4 positive NB8 cell line." (PMID 17925864, 2007). "The difference observed between the CXCR4 growth-promoting effects in vitro and in vivo indeed suggests that CXCR4 participates to a more complex growth-promoting phenomenon involving the tumour microenvironment." (PMID 17925864, 2007). "Parental lines and CXCR4 transduced clones were analysed in vivo for primary (orthoptopic) tumour growth, metastatic dissemination, and organ specific secondary growth." (PMID 17925864, 2007). "Strong CXCR4 expression did correlate with local progression and proliferation of the primary tumour as indicated by the T-status (TNM classification; P=0.006), with lymph node involvement (N-status; P=0.005) and with distant metastases (M-status; P=0.009)." (PMID 16819541, 2006). "While increasing evidence has suggested the pivotal role of CXCL12/CXCR4 biological axis in tumor metastasis, the specific mechanisms regulating CXCR4 expression in different tumors are poorly understood." (PMID 17083723, 2006).
tumor (continued). "Variables selected for this model were: CXCR4 expression, pT-, pN-, pM-category, histologic tumor type, tumor grading and the operative procedure (transthoracic versus transhiatal esophageal resection)." (PMID 17176471, 2006). "In HCC patients, CXCR4 expression significantly correlated with progressed local tumours (T-status; P=0.006), lymphatic metastasis (N-status; P=0.005) and distant dissemination (M-status; P=0.009), as well as with a decreased 3-year-survival rate (P=0.01)." (PMID 16819541, 2006). "Recent publications on CXCR4 are in line with the ‘homing’ theory as CXCR4 expression comediates dissemination of primary tumours to different organs through the chemotactic factors CXCL12." (PMID 16819541, 2006). "The chemokine receptor CXCR4 has been proposed to distinctly contribute to tumor growth, dissemination and local immune escape in a limited number of malignancies." (PMID 17176471, 2006). "It was recently shown that CXCR4 is involved in homing of tumour cells to specific organs and in tumour progression." (PMID 15987445, 2005). "As expected, staining of CXCR4 were seen in both normal and tumour cells, with staining in tumour cells being markedly stronger." (PMID 15987445, 2005). "On the other hand, tumour cells exposed to high concentrations of SDF-1 induce reduction in CXCR4 expression." (PMID 15987445, 2005). "Other reports have also shown that the SDF-1/CXCR4 biological axis is involved in regulating metastasis of tumours." (PMID 15987445, 2005). "More importantly, real-time RT–PCR analysis of 10 tumour samples and respective adjacent normal kidney tissue disclosed a distinct and divergent downregulation of CXCL12α and upregulation of CXCR4 in primary tumour tissue." (PMID 11953881, 2002). "All four cell lines as well as 10 primary human tumour samples plus adjacent normal kidney tissues were tested for CXCR4 and CXCL12α as well as for RPS9-mRNA expression." (PMID 11953881, 2002). "Preclinical and early clinical studies suggest that CXCR4 blockade can impair tumor growth, limit metastatic spread, and enhance chemotherapy and immunotherapy efficacy, although hematopoietic side effects and infection risk necessitate careful therapeutic design." (PMID 41750259, 2026). "At this stage, CXCR4+ TAMs then interact with cancer cells and induce expression of actin regulators, ultimately leading to the formation of podosomes in TAMs and invadopodia in tumor cells." (PMID 41438574, 2026). "Collectively, our findings demonstrate that CXCR4 blockade-mediated reprogramming of the perivascular tumor microenvironment promotes effective T-cell trafficking and function, providing a mechanistic rationale for combining oncolytic virotherapy with adoptive cell transfer in OC." (PMID 41679728, 2026). "[68Ga]Ga-TD-01 showed high tumor uptake (5.4 ± 4.3%ID/g at 9 min), low uptake in normal brain (2.2 ± 1.7%ID/g), and a tumor-to-background ratio of 2.9 ± 0.2 at 60 min, which was significantly reduced by CXCR4 blockade." (PMID 42162412, 2026). "Consequently, administration of a CXCR4 inhibitor during the circadian phase of elevated CXCR4 expression in tumor‐infiltrated CD8+ T cells promotes their dispersion throughout tumor tissues, thereby enhancing the efficacy of ICIs." (PMID 41257391, 2026). "On the other hand, chemokines and their receptors (e.g., CXCL12/CXCR4 axis) can play an important role in tumour biology, promoting metastasis, therapy resistance and shaping the immunosuppressive TME by enhancing inhibitory immune cells (Tregs, MDSCs) recruitment/infiltration." (PMID 41601679, 2026). "Furthermore, estrogen can increase SDF1 (also known as CXCL12) production in cancer cells and the TME, while the SDF1/CXCR4 signaling pathway has been shown to activate ER and promote hormone-independent tumor growth." (PMID 41597220, 2026).
tumor (continued). "Stemness, tumorigenicity and Epithelial-Mesenchymal Transition (EMT) profiles were established for cells in tumor spheres by flow cytometry (CD133/CXCR4), functional assays, Quantitative Reverse Transcription Polymerase Chain Reaction (RT-qPCR) and Western blotting." (PMID 41895102, 2026). "Furthermore, it has been noted that pharmacological inhibition of CXCR4 also potentiates the effect of ICIs, including anti-PD-1 and PD-L1, in reversing tumor-induced immunosuppression." (PMID 41383468, 2025). "This combination builds on the concept that the CXCR4 blockade may increase immune infiltration in the tumour microenvironment via reduction in T regulatory cells and myeloid-derived suppressor (MDSC) cells, thus promoting the activity of PD-1 inhibitors." (PMID 41002447, 2025). "Additionally, olaparib treatment downregulated CXCR4 in EGFRvIII+ tumor cells and SDF1α in CAFs, reducing MDSC migration and potentially improving therapeutic outcomes." (PMID 40281554, 2025). "Furthermore, the CXCL12/CXCR4 crosstalk between macrophages and lymphocytes was significantly amplified in the tumor context, providing deeper insight into the complex interplay driving the TME dynamics." (PMID 40698080, 2025). "Additionally, neutrophils gather in premetastatic niches via CXCR2 or CXCR4-dependent mechanism and release oncostatin M, elastase, and S100A8/S100A9, which causes tumor cell proliferation." (PMID 40016853, 2025). "In particular, combining CXCR4 blockers with alemtuzumab may improve its effectiveness by making tumor cells easier to target and helping immune cells reach the tumor." (PMID 41009972, 2025). "CXCR4 blockade has been shown to increase immune cell infiltration in tumours." (PMID 41002447, 2025). "Meanwhile, MSCs overexpressing CXCR4, when loaded with chemotherapeutic agents such as paclitaxel, not only preserve their inherent tumor tropism but also substantially boost drug accumulation within the tumor microenvironment." (PMID 41301162, 2025). "While CXCR4 on tumor cells promotes progression and metastases, its role on different immune cell subsets in the peripheral blood may have distinct implications for immunotherapy response." (PMID 41149503, 2025). "Deeper spatial penetration of shrunk nanogel (PAC-PTX) could block cell membrane CXCR4,thus decreasing the recruitment of immunosuppressive cell,as well as internalize into tumor cells for tumor-killing and T-cell priming." (PMID 40055311, 2025). "Notably, CXCL12 is the only confirmed ligand for CXCR4, a key receptor broadly expressed across multiple tumor types." (PMID 40860200, 2025). "The data from this study could open up CXCR4-targeted personalized therapies for CXCR4-positive tumor vessels." (PMID 41445742, 2025). "Additionally, Tc17 cells stimulate the release of the chemokine CXCL12 from tumor cells, which in turn recruits CXCR4+ MDSCs." (PMID 40452847, 2025). "Inhibition of this pathway has been demonstrated to reduce metastasis in breast cancer, likely through the disruption of CXCL12/CXCR4 signaling, which impairs chemotactic and invasive responses of tumor cells and limits their spread to regional lymph nodes and lungs." (PMID 40943634, 2025). "It includes CD40 agonists, CSF-1R inhibitors, CD11b agonists, CCR2 inhibitors, BTK inhibitors, and emerging chemokine receptor inhibitors, such as CXCR2 and CXCR4 antagonists, highlighting the diverse immune modulating approaches to reprogram the immunosuppressive tumor microenvironment." (PMID 40458409, 2025). "Combining anti-CXCR4 or anti-TGF-β with standard anti-PD-1 therapy may enhance anti-tumor immune response in EwS." (PMID 40242222, 2025). "All these findings considered, we speculate that tumor cells benefit from NK cells expressing CXCR4 and S1PR5 in two ways: retaining NK cells in the tumor periphery and desensitizing NK cells to stimulation before they reach the tumor stroma." (PMID 40155684, 2025).
tumor (continued). "A recent study demonstrated that targeting CXCR4 could enhance the efficacy of PD-1 immunotherapy by modulating the tumor microenvironment, primarily through the reduction of myeloid-derived suppressor cells." (PMID 40607416, 2025). "Furthermore, CXCL12 expressed by tumor-activated LECs in both axillary LN and lung can also attract CXCR4-expressing melanoma CSCs, thereby promoting metastatic growth." (PMID 40740784, 2025). "Moreover, CXCR4 plays a role in modulating the tumor immune microenvironment, contributing to immune suppression." (PMID 41149503, 2025). "In triple-negative breast cancer (TNBC), CAFs recruit monocytes to the tumor site through the CXCL12/CXCR4 axis and facilitate the progression of monocytes to immunosuppressive stabilin 1 (STAB1)+ lipid-associated macrophages, which are related to resistance to PD-1 blockade." (PMID 40453088, 2025). "Moreover, MMP2 was overexpressed in the early and late stages of tumor progression in the stromal area, and CXCR4 and CXCL12 were enriched after mid-stage progression inside the tumor." (PMID 39965034, 2025). "Additionally, AMD3100 has been used in antitumor studies, as CXCR4/CXCL12 is highly expressed in specific tumor cells." (PMID 40308758, 2025). "Studies have demonstrated that targeting this axis—through the inhibition of C-X-C Chemokine Receptor Type 4 (CXCR4) or TGF-β signaling—can remodel the tumor stroma, enhance CD8+ T cell infiltration, and improve the effectiveness of immune checkpoint blockades." (PMID 40940809, 2025). "Since MDSCs can induce apoptosis in CD8+T cells and impede the cytotoxic activity of CAR-T cells, the enhanced retention of CD8+T cells in tumor tissues observed in mice treated with CXCR4 CAR-T cells may be attributed to the reduced recruitment of MDSCs." (PMID 41368628, 2025). "Additionally, a combination of AMD3100 (a CXCL12/CXCR4 axis inhibitor) and anti-PD-1 therapy significantly reduces tumor growth, suggesting that circ_0020710 contributes to immune evasion through the CXCL12/CXCR4 signaling axis." (PMID 40739089, 2025). "Additionally, HIF regulates the expression of MMPs (matrix metalloproteinases), integrins, CXCR4 (C-X-C chemokine receptor type 4), and others to enhance the ability of tumor cells to survive and invade other tissues." (PMID 39935791, 2025). "CXCR4 also play significant roles in mobilizing Tregs to tumor locations in OSCC." (PMID 41445742, 2025). "It is worth noting, CXCR4 plays a key role in tumor angiogenesis required for OSCC progression." (PMID 41445742, 2025). "Inhibiting the CXCL12/CXCR4 axis may provide a strategy to limit tumor growth and prevent metastasis in patients with CRC." (PMID 40426863, 2025). "Lastly, in a third developing approach in addressing CXCR4/CXCL12-mediated drug resistance in TNBC, pharmaceutical engineers are developing a nanoparticle-based delivery system to selectively direct the CXCR4 inhibitors and chemotherapeutics to the tumour tissue to limit systemic toxicity." (PMID 41002447, 2025). "While our in vivo experiments confirmed the potential impact of CXCR4 inhibitor and IL-2 treatments on modulating immune cell dynamics and restricting tumor progression, the precise molecular mechanisms orchestrating these changes require further investigation." (PMID 40698080, 2025). "We targeted CXCR4, a chemokine receptor involved in tumor growth and metastasis." (PMID 40661577, 2025). "For example, CXCL9/CXCR3, which is known to recruit cytotoxic T cells, may counteract the tumor‐promoting effects of CXCL12/CXCR4 by enhancing anti‐tumor immunity." (PMID 40145607, 2025). "However, the immune-incompetent TME is potentially preventing proper anti-tumour immune responses as can be seen with high levels of CXCR4 on the B cell compartment, potentially restricting their access to the tumour core via retention outside." (PMID 39915477, 2025).
tumor (continued). "Importantly, the CXCL12/CXCR4 axis has become an important drug target for tumor therapy due to its critical role in cancer stem cell maintenance." (PMID 41445742, 2025). "CXCL12 plays a nuclear role in tumor-intrinsic EMT, invasion, survivability, and metastatic seeding mediated by tumor intrinsic CXCR4 signaling (through PI3K/AKT, MAPK/ERK, JAK/STAT) as well as CXCL12 chemotaxis induced by microenvironmental CXCL12 in stromal and endothelial cells." (PMID 41383468, 2025). "However, although many tumor suppressor or oncogenic miRNAs targeting CXCR4 have been identified, their clinical applications have been hampered mainly due to oligonucleotide degradation in the bloodstream and off-target toxicities." (PMID 40307933, 2025). "Moreover, MIF, through binding with CD74 and CXCR4, facilitates tumor cell migration and invasion and regulates the immunosuppressive state in the tumor microenvironment." (PMID 40110199, 2025). "Importantly, the tumor microenvironment (fibroblasts, endothelial cells, immune cells) is also dysregulated by CXCR4+ epithelial cancer cells." (PMID 40307933, 2025). "Notably, overexpression of CXCR4 was sufficient to reverse the immune‐activating and tumor‐inhibitory effects of the NPs." (PMID 40536774, 2025). "Conversely, low circulating CXCR4-expressing cytotoxic T lymphocytes may correlate with increased tumor infiltration and better immunotherapy benefit." (PMID 41149503, 2025). "High levels of CCR2, CCR5, and CXCR4 at 1 week further supported active DC trafficking toward lymphoid tissues and tumor sites, while increased IL-10 may reflect early regulatory feedback within an immunostimulatory context." (PMID 41278869, 2025). "The CXCL12/CXCR4 axis participates in numerous cellular functions, including cell proliferation, migration, and differentiation, and has been thoroughly investigated in several tumours and autoimmune diseases." (PMID 39779470, 2025). "The interaction between CXCL12 and CXCR4 promotes tumor growth and metastasis." (PMID 41439026, 2025). "Additionally, CXCR4 blockade combined with standard chemotherapy produced a synergistic anti-tumour effect, underscoring the axis’s potential as a therapeutic target." (PMID 41002447, 2025). "Notably, CXCR4 is found to be highly overlapped with CD105+ angiogenic tumor vessels among various vascular markers." (PMID 41210695, 2025). "Together with our results, it seems that EGR1 and CXCR4 might be actively secreted into small EVs by CRC tumor cells to subsequently participate in intercellular communication and provide an optimal microenvironment for the establishment of distant metastases." (PMID 40635521, 2025). "Moreover, we further analyzed the mRNA levels of Cd74 and Cxcr4 in tumor tissues of the mouse Hepa1‐6 implantation models." (PMID 40018995, 2025). "Tumor effector memory CD8 T cells demonstrated overexpression of CCR7, IL7R, and CXCR4, which are associated with a naïve-like T cell state and inversely associated with T cell polarization and effector T cell function, as well as TXNIP, which negatively regulates T cell proliferation." (PMID 40848148, 2025). "These facts suggest that miRNAs that regulate CXCR4 could be used to inhibit metastasis and tumor progression in multiple cancers." (PMID 40307933, 2025). "Compared to the oe‐NC group, the number of CD4+ T cells and CD8+ T cells was significantly increased in the tumor tissues of mice in the oe‐NC+M2pep‐Cs NPs/Plerixafor group; while, these numbers were significantly decreased in the tumor tissues of mice in the oe‐CXCR4 group." (PMID 40536774, 2025). "Notably, the CRAd-S-pk7 modification enhanced NSC homing to the tumor upon intracranial administration through upregulation of CXCR4 and VEGFR2 on NSCs." (PMID 40723180, 2025). "The CXCL12/CXCR4 axis has been confirmed to regulate tumor metastasis in different tumors." (PMID 41142609, 2025).